PIK3CA (phosphatidylinositol-4,5-bisphosphate 3-kinase catalytic subunit alpha)
Diseases named in the same sentence as PIK3CA in open-access papers (continued):
Sharing a sentence is not in itself a finding about the gene and the disease.
tumor (continued). "Among the 16 cases of OCCC with PIK3CA mutation in the tumor, 14 cases had analyzable eutopic endometrium." (PMID 34172890, 2021). "Mutations in the AKT1, PIK3CA, and BRIP genes were associated with tumor recurrence, with a highly pathogenic variant in PIK3CA being particularly prominent." (PMID 34680380, 2021). "PIK3CA variants seem to relate to tumor burden in the index patients, marked by an increase in VAF at PD, and a dramatic decrease in VAF after successful chemotherapy." (PMID 33494385, 2021). "The PIK3CA mutations in three hotspots in the tumor were mutually exclusive, which is a natural result as oncogenic driver mutation." (PMID 34172890, 2021). "In HCC PIK3CA is mutated in 28% to 35.6% of cases, but there are limited studies defining the percentage of cells with PIK3CA mutations within each tumor." (PMID 34771685, 2021). "At least one of three PIK3CA missense mutation spots was detected in 10 (41.7%) of 24 tumor DNA samples, 7 (30.4%) of 23 circulating DNA samples collected before treatment, and 12 (29.3%) of 41 DNA samples collected during follow-up after treatment." (PMID 34203201, 2021). "The PALOMA-3 trial assessed endocrine therapy resistance by tumor PIK3CA mutational status in circulating DNA at baseline, but neither the PIK3CA status nor the hormone receptor expression level significantly affected the treatment response." (PMID 33923563, 2021). "PIK3CA gene mutations were assessed in archival tumour tissue and serially in plasma circulating tumour DNA over the course of treatment with copanlisib." (PMID 33799597, 2021). "Our mutational analysis shows FGFR3 mutation both on epididymal BT and liver metastasis, while PIK3CA mutation was only present in the primary tumor." (PMID 33912469, 2021). "The identification, in our cohort, of a possible association between the prognostic impact of γδ T cell infiltration and PIK3CA mutational status highlights the complex cross-talk between oncogenic signaling pathways and anti-tumor immunity." (PMID 33673133, 2021). "All variants found in tumor 2 were also observed in cell 2 (two variants of PIK3CA and one of FGFR1)." (PMID 33917394, 2021). "Mutational activation of PIK3CA detected in tumor tissue has been found in association with both an adverse clinical outcome of patients in multiple solid tumors and can predict a favorable response to PIK3CA inhibitors." (PMID 34203201, 2021). "Reduction of proteins encoded by NFKB1 and PIK3CA have been shown to aid in tumor survival and growth." (PMID 34968392, 2021). "For example, if eutopic endometrial cells with PIK3CA mutation as an oncogenic driver are the origin of OCCC, then all tumor cells of OCCC would have the PIK3CA mutation." (PMID 34172890, 2021). "We found that in three of the four cases with low CDKN2A mRNA expression but strong p16 protein staining, the tumor harbors either PIK3CA mutation, PIK3CB amplification or loss of PTEN gene (case B6, NB7, NB8)." (PMID 34948172, 2021). "Molecular profiling of the tumours (both primary and metastases) to assess for gene alterations like mutations in PIK3CA will be recorded as well as immune profile of the tumours, if available." (PMID 34544470, 2021). "The sequencing of protein-coding exons, e.g., KRAS, BRAF and PIK3CA, in circulating tumor DNA (ctDNA) samples from MM patients revealed that it predicted 96% of mutations detected in matched BM-derived tumor DNA samples with >98% specificity." (PMID 34299097, 2021). "PIK3CA H1047R mutation was found in 12% (10/83) of total samples and 14.3% (10/70) of tumor samples." (PMID 34359206, 2021). "PIK3CA activating mutations lead to hyperactive signaling downstream of mTORC1, and suggest a tumor-promoting function for mTOR signaling in TNBC25." (PMID 34031411, 2021).
tumor (continued). "Studies also suggested that the most common mutational hotspots of PIK3CA are located in exon 20, and a regional association between the PIK3CA mutation and the tumor site (i.e., lower alveolus and lower lip) has been observed." (PMID 33023080, 2020). "Early studies showed that Bup exhibited preferential inhibition of tumor cells bearing PIK3CA mutations, in contrast to either KRAS or PTEN mutant models." (PMID 32825725, 2020). "PDX153 was the only PDX with an oncogenic PIK3CA mutation (p.K111E) reported to confer sensitivity to the treatment, and indeed, we observed a significant reduction of 83% in the tumor volume after 35 days of treatment (i.e., a PR outcome)." (PMID 32907621, 2020). "PIK3CA mutations occurred in 32% of patients, displayed a significant association with ER positivity, increasing age, lower grade and smaller tumor size." (PMID 32210163, 2020). "A phase III clinical trial showed how patients with advanced tumours and mutations in PIK3CA benefited from the use of alpelisib in combination with fulvestrant; compared with fulvestrant with placebo, this combination increased the PFS and response rates." (PMID 32211045, 2020). "Dysregulation of PI3K signalling—stemming from activating mutations or amplifications of PIK3CA—leads to constitutive activation of the pathway, which can promote tumor development and progression." (PMID 33059733, 2020). "Conversely, Alp selectively inhibits proliferation of PI3Kα-driven HR+ HER2− BC cells and causes regression of PIK3CA-mutated in vivo tumor models." (PMID 32252811, 2020). "In BELLE‐2,19 detection of PIK3CA mutations in ctDNA clearly outperformed analysis of PIK3CA mutations or loss of PTEN expression in archival tumor specimens." (PMID 32352244, 2020). "When analyzing tumor DNA extracted from the primary tumor, a focused next-generation sequencing approach detected a PIK3CA mutation in exon 10 (c.1624G > A p.Glu542Lys;p." (PMID 32854635, 2020). "Cancer-specific mutations such as K-Ras and PIK3CA carried via circulating tumor DNA have been found in urine samples with higher sensitivity than in plasma or serum." (PMID 32498309, 2020). "While mutation frequencies in oncogenes such as PIK3CA are generally in line with previous reports, frequencies in tumor suppressor genes were generally lower in RNA‐seq than would be expected from our study population." (PMID 32926574, 2020). "According to the data from the TCGA database PIK3CA is the second most commonly mutated gene in human neoplasias, with the highest frequency in uterine, breast and head and neck carcinomas." (PMID 32545208, 2020). "The determination of PIK3CA gene mutational status in tumor tissue specimens was mandatory before patient enrollment." (PMID 32252811, 2020). "At present, however, alpelisib is the only MTA that requires identification of PIK3CA mutation in the tumor to predict its efficacy." (PMID 32881420, 2020). "Similar helical domain biases have also been reported for PIK3CA mutations in other APOBEC-signature tumour types, implying as the common denominator the APOBEC mutagenesis and not viral infection." (PMID 33292100, 2020). "While alpelisib was only effective in patients with PIK3CA-mutated neoplasms, retrospective analyses indicate that everolimus improves exemestane efficacy independently of PIK3CA mutational status." (PMID 32252811, 2020). "Tumor 5 had a high confidence PIK3CA:p.H1047R:c.3140A>G somatic mutation resulting from the substitution of histidine (H) by arginine (R) at position 1047 of the PIK3CA gene." (PMID 32426287, 2020).
tumor (continued). "We reported that PIK3CA mutations are associated with increased tumor aggressiveness and AKT activation in patients with GC9." (PMID 32704014, 2020). "Mutated tumor-suppressor genes, such as phosphatidylinositol-4,5-bisphosphate 3-kinase catalytic subunit alpha (Pi3kca), Neurofibromin 1 (Nf1), and Lrig1 were observed." (PMID 32059662, 2020). "The most common source of tumor DNA for identifying PIK3CA mutations among the HR+/HER2-mBC subgroup was tumor tissue biopsies (n = 36)." (PMID 32637176, 2020). "Clinical trial studies have shown that PIK3CA mutations are associated with increased tumor aggressiveness, especially in locoregional disease, and Akt activation in GC." (PMID 32020871, 2020). "Monotherapy with PI3K/mTOR dual inhibitors is of interest in tumor types with a particularly high incidence of aberrant PI3K pathway activation by PIK3CA mutations, amplification, or loss of PTEN tumor suppressor protein." (PMID 32578154, 2020). "Despite these limitations, our results are the first to assess the interplay of aspirin, PIK3CA tumor mutations, and outcomes, and can serve to inform further investigation of these associations." (PMID 32326897, 2020). "The combination was clearly superior in patients with PIK3CA‐mutated HR + mBC as detected in tumor DNA (median PFS: 11 months vs 5.7 months; ORR: 36% vs 16%) or in cfDNA (median PFS: 10.9 months vs 3.7 months; ORR: not reported)." (PMID 32352244, 2020). "If this independence is confirmed, more patients would be eligible for capivasertib than alpelisib therapy, which is approved only in patients with tumours harbouring PIK3CA mutations." (PMID 32035020, 2020). "PIK3CA-activating mutations have been detected in 8/91 (9%) malignant PitNET, but in 0/262 benign tumors, making this gene an indicator for invasive tumor progression." (PMID 32498309, 2020). "Another finding was that loss of 9p21.3 in 64.3% of all MpBC tumor samples was accompanied by a concurrent PIK3CA mutation." (PMID 33148288, 2020). "Alpelisib is an oral selective PIK3α isoform inhibitor, exhibiting dose-dependent antitumor activity in preclinical models, including tumor xenograft models, with more pronounced activity against PIK3CA-mutated tumors." (PMID 32210163, 2020). "Since tumor PIK3CA mutation status has been shown to change over time in response to various lines of treatment, better understanding of the prevalence of PIK3CA mutation timeline is warranted, particularly in HR+/HER2– tumors." (PMID 32637176, 2020). "Here, we report a novel strategy with proof-of-concept data that supports the usage of loop-mediated isothermal amplification (LAMP) to detect PIK3CA c.3140 A > G (H1047R), a prevalent BC missense mutation that is attributed to BC tumour growth." (PMID 32165708, 2020). "This was well demonstrated by significant in vivo and ex vivo anti-tumor effect in PIK3CA-mutated PDXs, which acquired resistance over time upon exposure to PI3Ki as well as PK3CA-WT PDXs treated with combination therapy." (PMID 33036331, 2020). "In our study, PIK3CA mutation analysis of tumor‐derived DNA provided a strong signal as a positive predictive biomarker for benefit from buparlisib/tamoxifen combination." (PMID 32352244, 2020). "Among the four subtypes, EBV-positive tumor was associated with mutations in PIK3CA and ARID1A genes and elevated PD-L1 expression." (PMID 32824568, 2020). "While PTEN expression was studied in formalin‐fixed paraffin‐embedded (FFPE) tumor biopsies, somatic PIK3CA mutations were assessed in tumor tissues as well as in DNA freely circulating in the bloodstream (cfDNA)." (PMID 32352244, 2020). "As we expected, clinical benefit was only observed in patients whose tumours harboured PIK3CA mutations." (PMID 32641355, 2020). "Third, the analyzed datasets were mostly from primary tumor samples and acquisition of new PIK3CA mutations has been described in the metastatic setting in 8–10% of the cases." (PMID 32404150, 2020).
tumor (continued). "There was a positive association between PIK3CA and PTEN mutations in the BSA group, with 78% of PIK3CA-mutant tumours harbouring a PTEN mutation, whereas only 11% of PIK3CA wild-type (wt) tumours were PTEN mutant positive (p = 0.0012)." (PMID 32520976, 2020). "Missense mutation of PIK3CA pathway components are involved in tumor development and occur in many cancer types." (PMID 32631368, 2020). "Consistent with SOLAR-1 results, these studies reported an incidence of G3/G4 hyperglycemia and rash in the 10–38.1% and 8–27.8% ranges, respectively, with longer mPFS in patients with PIK3CA-mutated neoplasms." (PMID 32252811, 2020). "We also found that cell cycle arrest, proliferation, and migration inhibition, and apoptosis contributed to the anti-tumor activity of abemaciclib/BYL719 combination therapy in the PIK3CA mutated CRC cells." (PMID 32899250, 2020). "Intratumor heterogeneity, which refers to the coexistence of cell clones harboring variable genetic mutations within a tumor, is another reason for characterizing novel and rare PIK3CA mutations." (PMID 32365913, 2020). "Of note, tumor harboring PIK3CA mutations were affected to a lower extent by the combination of BMP7v and chemotherapy." (PMID 31591478, 2020). "PIK3CA gene amplification is associated with advanced stage of tumor and overall poor disease-free survival." (PMID 32974170, 2020). "Common genetic alterations in HPV-positive HNSCC include loss of TRAF3, amplification of E2F1, and a higher rate of PIK3CA mutations than HPV-negative tumours." (PMID 33322840, 2020). "Among women who develop metastatic breast cancer, tumor PIK3CA mutations are associated with slower time to progression and mortality only among aspirin non-users." (PMID 32326897, 2020). "The relationships among PIK3CA mutations, medication use and tumor progression remains poorly understood." (PMID 32326897, 2020). "In the BOLERO-2 study, PIK3CA mutation analysis in archival tumour samples of 302 patients has revealed that median PFS was longer for wild-type PIK3CA carriers in both treatment arms." (PMID 32566979, 2020). "The SOLAR-1 phase III trial that led to the approval of alpelisib used the therascreen PIK3CA 11-mutation assay in tumor tissue to identify PIK3CA mutations." (PMID 32404150, 2020). "In patient 3, a PIK3CA variant, p.E726K, was detected only in tumour #2, and the variant allele frequency was 14%." (PMID 31929516, 2020). "Our group previously reported that PIK3CA mutations were associated with increased tumor aggressiveness and AKT activation in patients with GC9." (PMID 32704014, 2020). "PIK3CA mutation profiling in both plasma and urinary cell-free DNA showed an agreement of 97.2% compared with the results obtained for tumor tissues." (PMID 33044511, 2020). "Oncogenic mutations in PIK3CA lead to deregulation of the phosphatidylinositol 3-kinase-Akt signalling pathway, including tumour development, cell survival and cellular transformation, and are reportedly the most common genetic alterations in CC12,15." (PMID 33127935, 2020). "We assessed time to metastasis (TTM) and survival with respect to aspirin use and tumor PIK3CA mutations among women with metastatic breast cancer." (PMID 32326897, 2020). "In this study, ESR1 mutations were observed in 37% of baseline tumor samples: these mutations are clearly enriched in luminal A (72%) and PIK3CA-mutant (60%) patients." (PMID 32210163, 2020). "For instance, four of seven tumours with a PIK3CA mutation presented this mutation in each component." (PMID 32058674, 2020). "The presence of PIK3CA mutations confers clinical-pathological characteristics favorable to tumors such as small tumor size or low grade; and therefore, the reason for an unfavorable prognosis of NEBC is almost partially explained." (PMID 32414120, 2020).
tumor (continued). "Three major hotspot mutations in PIK3CA are reported in IDC tumor samples, the H1047R, E545K, and E542K mutations, with reported mutation frequencies of 10.52%, 5.41%, and 3.22%, respectively." (PMID 30813596, 2019). "The trial also assessed endocrine therapy resistance by clinical parameters, quantitative hormone receptor expression, and tumor PIK3CA mutational status in circulating DNA at baseline." (PMID 31450618, 2019). "The third mouse generation of YHIM-1009 (EGFR 19del mutation/ PIK3CA E542K) tumor model, an acquired-gefitinib resistant tumor, was used for drug efficacy testing." (PMID 31043587, 2019). "Univariate analysis revealed that PIK3CA E545K mutation, tumor location, and tumor stage were associated with a significantly shorter OS." (PMID 32099598, 2019). "A PIK3CA T1035A mutation present in a BC-PDX tumor was confirmed in isolated single CTCs and cells from dissociated metastatic nodules after whole genome amplification and sequencing." (PMID 30871481, 2019). "Further, PIK3CA mutations, frequently detected in cfDNA in breast cancer and an indicator of tumour burden and treatment efficacy have been a subject of interest since they also show high concordance between cfDNA and metastatic tumours." (PMID 31817150, 2019). "Significant correlations were observed in PIK3CA E545K mutation with tumor differentiation and TNM stage (p < 0.042 and p = 0.033, respectively)." (PMID 32099598, 2019). "As T-DM1 binds to HER2, theoretically, T-DM1 is more likely to kill a PIK3CA-mutated tumor cell with co-occurring HER2 amplification versus a HER2-negative, PIK3CA-mutated cell, despite the fact that the tumor as a whole is HER2-positive and PIK3CA-mutated." (PMID 31146717, 2019). "Similar to other tumor types, recent genome-wide studies have revealed that both mutations of PIK3CA and deletion/downregulation of Pten occur in human HCCs." (PMID 30975125, 2019). "All patients with PR had PIK3CA-mutated tumor, which suggested that taselisib is expected to be effective in patients with PIK3CA-mutated solid tumor." (PMID 30782187, 2019). "Regardless, we demonstrate that elacestrant inhibits growth in models with upregulated, downregulated Rb or Rb-null cells and is able to produce significant TGI in models with ER-driven tumor cell growth and PIK3CA mutations." (PMID 31852484, 2019). "In this dataset of ER-positive breast cancer, tumor infiltration of CD8-positive lymphocytes was associated with PIK3CA mutations and worse clinical outcome." (PMID 31391067, 2019). "For example, an oncogene, such as PIK3CA, is usually affected by activating mutations or copy number amplifications, whereas a tumor suppressor, such PTEN, is usually affected by inactivating mutations or copy number deletions." (PMID 31276486, 2019). "The primary endpoint was PFS in patients with PIK3CA mutations detectable in tumor tissue (n = 341)." (PMID 31396487, 2019). "The precise molecular mechanisms that contribute to tumor development in the context of FAT1 functional loss or PIK3CA overexpression are not fully understood." (PMID 31817001, 2019). "There was enrichment for PIK3CA mutations in R258G tumours, and PIK3R1 in G356D (log2 odds ratios >2.5), however this failed to reach statistical significance." (PMID 31098401, 2019).